IL2 (interleukin 2)
Diseases named in the same sentence as IL2 in open-access papers (continued):
Sharing a sentence is not in itself a finding about the gene and the disease.
tumor (continued). "It has been reported that inhibiting autophagy during interleukin 2 (IL-2) immunotherapy can promote long-term tumor regression by tumor inhibition and enhance immune cell proliferation and infiltration." (PMID 32322202, 2020). "Hu14.18-IL2 is a synthetic fusion protein consisting of an anti-GD2 tumor-specific antibody genetically fused with IL2, an immune-stimulating cytokine." (PMID 32849544, 2020). "In this study, we describe the superior anti-tumor efficacy of NKTR-214 compared to IL-2 to support the antitumor activity of adoptively transferred T cells in a preclinical model." (PMID 32005809, 2020). "Administration of (MS@OVAinMOF)@(polyICinMOF) plus a low dose of i.p. anti-PD-1 (group f) stimulates IL-2 secretion in the tumour of mice." (PMID 32737343, 2020). "Our study showed that the expression of immune-related cytokines IFN-γ and IL-2 in the tumor microenvironment affects the therapeutic effect of PD-1." (PMID 32425919, 2020). "NKG2D has a dual function in NK cell cytotoxicity; while NKG2D is a crucial trigger for cytotoxicity against tumor cells expressing activating ligands, it limits perforin production in IL‐2 activated NK cells." (PMID 32052406, 2020). "Both formats displayed a potent tumor growth inhibition compared to the saline control and to the untargeted recombinant interleukin-2." (PMID 33110477, 2020). "show that upon depletion of regulatory T cells, a surplus of interleukin-2 in the tumor microenvironment supports acquisition of cytotoxic activity by T helper cells orchestrated by the transcription factor Blimp-1." (PMID 31924474, 2020). "This nanovaccine was prepared by encapsulating IL‐2‐loaded PLGA‐NP with the cell membrane derived from tumor cell lysate‐pulsed mature DCs." (PMID 32274314, 2020). "As expected, anti-PDL1 favored the induction of an immune response within the tumor as highlighted by Tnfa, Il6, Ifng, Il2, and Tgfb induction—Ifng expression levels being significantly correlated with survival (Data not shown)." (PMID 32194552, 2020). "For TIL therapy, T cells that recognize cancer-specific antigens are collected from tumor tissues in patients with cancer, artificially reactivated by using T cell-stimulating agents, such as a high IL-2 concentration, and are then returned to the patients." (PMID 33282961, 2020). "We found that MB treatment dramatically enhanced expression of perforin, granzyme B (GZMB), and IL‐2 by CTL in tumor nodules." (PMID 32391629, 2020). "Clinical trials based on vaccination with 210 M antigen, alone or in combination with interleukin-2 (IL-2), have demonstrated the induction of peptide- and tumor-specific cytotoxic T-lymphocyte responses in peripheral blood." (PMID 33080888, 2020). "In this review, we discuss the distinct roles of IL-2 and IL-15 in activating various functions in T and NK cells with a particular focus on the signals that participate in the resistance of tumor-derived immune suppressive factors." (PMID 33266177, 2020). "Here, the authors show that ex vivo polarized Th9/Tc9 human CAR-T cells display increased anti-tumor activity in pre-clinical haematological and solid cancer models compared to conventional IL-2 activated CAR-T cells." (PMID 33214555, 2020). "The resulting dose-dependent increase in IL-2 production by Jurkat cells co-cultured with PD-L1 expressing tumor cells in samples treated with TF-Fc peptide is consistent with successful blockage of PD-1/PD-L1 binding." (PMID 33182232, 2020). "Early studies in tumour infiltrating lymphocytes expanded in IL-2 involved the co-administration of high dose IL-2, which was deemed to be essential for their persistence following adoptive transfer." (PMID 32824734, 2020). "Alternatively, CD40 antibodies have been combined with IL-2 immunotherapy as a strategy to induce tumor-specific T cell immunity in tumor models of renal cell adenocarcinoma or Lewis lung carcinoma." (PMID 35582441, 2020).
tumor (continued). "To test this principle, we used the pre-clinical pmel-1 mouse model to study the behavior of tumor-specific CD8 T cell expansion when NKTR-214 is combined with ACT compared to ACT + IL-2." (PMID 32005809, 2020). "High doses of IL-2 has been used for T cell culture for more than 20 years, and were found to promote growth of tumour reactive T cells." (PMID 32183246, 2020). "On the other hand, it was shown that CD4+ T cells expressing an MHC class I‐restricted TCR provide important additional TCR functions, such as increased IL‐2 help, and thereby contribute to an increased anti‐tumor response." (PMID 33251011, 2020). "In vitro transduction of tumor cells with the IL-2 gene was achieved using viral vectors (e.g., retro-viral or adenoviral) or by employment of advanced methods like the adenovirus-enhanced transferrinfection (AVET) system." (PMID 32917034, 2020). "The exact mechanism of action of intralesional IL2 is unclear, as the scarcity of data limits our understanding; however, there is likely an anti-tumor T cell response that triggers clearance of malignant melanocytes." (PMID 32455916, 2020). "Studies in mouse models have shown successful anti-tumor effects when IL-2 was combined with regulatory T cell (Treg) depletion by monoclonal CD25 antibody." (PMID 33138229, 2020). "The use of MSCs as a vehicle for the delivery of therapeutic agents can increase the effectiveness of IL2-based immunotherapy by stimulating an antitumor immune response or directly inhibiting tumor growth." (PMID 32560387, 2020). "The binding of TIM-3 by galectin-9, a soluble s-type lectin, triggers an exhausted phenotype characterized by low proliferation and secretion of IL2 and IFNγ in tumor infiltrating CD4+ and CD8+ cells." (PMID 32937953, 2020). "Paul Karl Horan (PKH-26)-labeled and IL-2/HSP70-treated NK cells demonstrated a potent ability to target GFP-expressing GBM cells within the tumor." (PMID 32218162, 2020). "Pre-clinical models of GBM have shown NK cells to be effective in HLA class I-mediated tumor lysis; IL-2 activated NK cells' ability to kill GBM cells, and NK cells' effectiveness in preventing metastasis in the GBM xenograft mouse model have been reported." (PMID 32765498, 2020). "From our analysis, we identified IL-2, IL-6, and TGFβ as the cytokines most significantly modulated by the tumor itself and by RT." (PMID 30658426, 2019). "HD IL-2 is an attractive target for such exploration since it is a therapy that has documented, single agent anti-tumor efficacy and prolonged duration of responses and survival." (PMID 30777131, 2019). "In recent years, new derivatives of IL-2 such as PEGylated IL-2 (NKTR-214) or IL-2 conjugated with tumor-targeting antibodies (IL-2-based immunocytokines) have found their way to the clinical testing." (PMID 31179236, 2019). "In tumor tissue, the number of FoxP3+ Tregs was positively correlated with IL-6 expression and negatively correlated with IL-2 and TNF-α expression (R2 = 0.0720, P = 0.0161; R2 = 0.1030, P = 0.0037; and R2 = 0.0507, P = 0.0446, respectively)." (PMID 31417548, 2019). "Following iv injection of ex vivo TKD/IL-2-stimulated, human effector cells (38.6 ± 9.7 days) a significant increase in the OS of tumor-bearing animals was observed compared to sham (PBS or IgG control antibody) treated control animals." (PMID 30967859, 2019). "Subsequent phase I clinical study demonstrated that treatment of tumor patients with autologous ex vivo HSP70-derived peptide plus IL-2 activated NK cells was safe and well tolerated." (PMID 31652993, 2019). "IL-2 inhibits tumor growth by enhancing immune cell proliferation and infiltration in the liver and spleen; however, the anti-tumor effects of HDIL-2 immunotherapy were significantly heightened when coupled with administration of autophagy inhibitor CQ." (PMID 30678689, 2019). "The model indicated that single therapy with large doses of IL-2 yielded to the tumor suppression and increased the number of effector cells." (PMID 30871264, 2019).
tumor (continued). "Taken together, the data suggests that the co-operation of signals from activating receptors and IL2 are crucial for modulating NK cell metabolism to facilitate the induction of robust and prolonged anti-tumour NK cell responses." (PMID 31595191, 2019). "Exposure to IL-2, IL-12, IL-15, or IL-12/15/18 induced a similar “trafficking” signature to that induced by tumor cells: CXCR4 and CD62L expression was downregulated compared to unstimulated NK cells." (PMID 31242243, 2019). "In a xenograft animal model with ovarian cancer tumor grafts, autologous, or allogeneic NK cells expanded with IL-2 and K562 feeder cells expressing IL-21 were infused." (PMID 31614472, 2019). "In this highly radiosensitive model, only slight differences were found for tumor-specific CD8+ TILs per gram tumor tissue between the hRT monotherapy, hRT/IL-2 and hRT/IL-2c combination groups." (PMID 30808414, 2019). "The PET imaging and biodistribution experiments helped to reveal that CD122/γc-directed IL-2c preferentially bind CD122+ cells outside of the tumor and that target binding in the tumor can be limited by IL-2 secreted by tumor-resident effector cells." (PMID 30808414, 2019). "In initial studies on adoptive T-cell therapy, IL-2 was widely applied for its stimulatory impact on T cells, promoting growth and survival of tumor-specific T cells administered to cancer patients." (PMID 31195686, 2019). "One of the earliest immunotherapies, high dose interleukin-2 (HD IL-2), activates T-cells and has documented durable tumor responses in a subset of patients with mM and mRCC." (PMID 30777131, 2019). "Another study showed that increased IL2 availability following the depletion of Tregs led to increased NK cell dependent tumour cell killing." (PMID 31595191, 2019). "Recently, IL-15 treated NK cells were shown to maintain anti-tumor activities in the context of an immunosuppressive microenvironment compared with IL-2 treated NK cells." (PMID 31340613, 2019). "Super-secreted (K35E) IL-2/Fc is biologically active in vitro and in vivo, has anti-tumor activity and exhibits a remarkable reduction in its aggregation propensity- the major manufacturability issue limiting IL-2 usefulness up to now." (PMID 30692603, 2019). "Concomitantly mice carrying metastatic tumours showed an increased serum IL-10/IL-2 ratio (Th2/Th1) after in vivo stimulation with anti-CD3 antibodies." (PMID 31683642, 2019). "TNF damages the tumor endothelium leading to a rapid hemorrhagic necrosis of the neoplastic mass, while IL2 mainly acts by activating NK cells and CD8+ lymphocytes." (PMID 31799191, 2019). "Despite their high cytolytic activity, hypoxic CAR-T cells produced relatively low levels of granzyme B, IFN-γ, IL-2, and IL-6 in response to transfected cells and tumor cell lines endogenously expressing the target antigen." (PMID 31052261, 2019). "The resected tumor was fragmented or enzymatically digested and subsequently cultured in the presence of IL-2, which resulted in proliferation of TIL." (PMID 30470934, 2019). "Disrupting mTORC1 and cMyc signalling in CD25high tumour interacting NK cells prevents IL2-induced cell growth and function and compromises NK cell viability." (PMID 31595191, 2019). "When administered locally in the tumor, IL-2 induces the release of pro-inflammatory mediators, increasing sensitivity to further immune attack." (PMID 31443604, 2019). "The release of the TGFβ inhibitor and IL2 significantly delayed tumor growth by promoting NK cell activation and CD8+ T cell infiltration in a murine B16F10 melanoma model." (PMID 31695803, 2019). "In this view, from published studies, radiolabelled IL2 represents a promising tool able to differentiate pseudo-progression and real tumour progression thus providing important information for therapy decision making." (PMID 31091813, 2019).
tumor (continued). "To further evaluate the contribution of Jarid2 in CD8+ T cell antitumor immunity we transferred pmel-1 Jarid2−/− CD8+ T cells into tumor-bearing mice in conjunction with gp100-VV and interleukin-2 (IL-2) administration." (PMID 31089138, 2019). "In this study, we found that IL-2 production by spleen cells of S-180 tumor-bearing mice was enhanced with increased PEC dose." (PMID 31334112, 2019). "Our results did not reveal any major effect of MPA on the anti-Aspergillus activity of human NK cells, corroborating studies investigating the effect of short-term MPA treatment (<24 h) on cytotoxicity of IL-2 activated NK cells towards tumor cells." (PMID 31752374, 2019). "Numerous animal tumor models have demonstrated broad anti-tumor activity for various cytokines, including GM-CSF, IL-2, IL-7, IL-12, IL-15, IL-18 and IL-21." (PMID 31856922, 2019). "The current TIL therapy consists of ex vivo expansion of TIL from resected tumor material and adoptive transfer into the patient following a lymphodepleting preparative regimen and subsequent support of interleukin-2 (IL-2)." (PMID 30470934, 2019). "Immunotherapy via cytokine infusion has also been extensively trialed, with IL-2, IL-12, and IFNα2b to activate T cells, showing anti-tumor effects in pre-clinical models and clinical trials, with IL-2 and IFNα2b approved for clinical use." (PMID 30941125, 2019). "Transduction of T cells in an early differentiation stage (central memory CD8+ T cells) seems to result in greater anti-tumor responses when combined with tumor-antigen vaccination and exogenous IL-2 in preclinical murine models." (PMID 30470934, 2019). "A transcriptome analysis and cytokine profiling of naive T cells stimulated by ATV-NDV tumor vaccine via attached αHN-αCD3 (for signal 1) and αHN-IL2 (for signal 2) revealed unsuspected costimulatory activity of the cytokine IL-2." (PMID 31480379, 2019). "Consistent with the tumor growth and survival data, T and NK cell numbers in mice treated with hRT + free IL-2 were generally more similar to those after hRT monotherapy." (PMID 30808414, 2019). "While the same molar of IL-2-Fc resulted in better tumor control than free IL-2, tumors become resistant to the treatment in 1–2 weeks." (PMID 31462678, 2019). "Serum SA and IL-2 levels are important indicators for the measurement of oral and maxillofacial tumor resection and tissue repair." (PMID 31489003, 2019). "IL-2, IL-15 and IL-21 conditioning of total TILs from the resected PanTT26 tumour piece (which includes the TLS) was enriched for CD8+ T cells, as confirmed in the cytotoxicity assay performed with the autologous tumour cell line." (PMID 30377343, 2019). "It consequently suggests that the presence of Treg cells inside the tumor limits the therapeutic effects of IL-2." (PMID 31462678, 2019). "Cish−/− mice react to IL-2 treatment with a further decrease of tumor burden in models that are usually unaffected by IL-2 treatment." (PMID 31781102, 2019). "In this study, the ability of NKTR-214 to preferentially bind to IL-2Rβ over IL-2Rα induces a greater CD8+ T cell to Treg cell ratio, greater exposure to IL-2 in the tumor and a more robust anti-tumor immunity in comparison to aldesleukin." (PMID 31058083, 2019). "Here, the authors develop a recombinant IL-2 immunocytokine which is comprised of a tumor-targeting antibody fused to a super mutant IL-2 and show in mouse models that this next-generation IL2 has reduced toxicity and enhanced antitumor activity." (PMID 31462678, 2019). "On the contrary, anti-inflammatory ILs (IL-2, IL-12, IL-10, and others) frequently activate antitumor immunity, thus interfering with tumor growth." (PMID 31847214, 2019). "RT‐PCR showed that in comparison to those from the shMACC1‐NC and shMACC1 groups, the expression of IFN‐γ and IL‐2 was increased and the expression of IL‐10 was decreased in tumor samples from the shMACC1 group." (PMID 31557409, 2019).
tumor (continued). "Compared with those from the vector‐NC group, the expression of IFN‐γ and IL‐2 was decreased and the expression of IL‐10 was increased in the tumor tissue samples from the MACC1 group; this difference was significant (P < .05)." (PMID 31557409, 2019). "This study reveals that tumour cell interactions and T cell-derived IL2 cooperate to promote robust and prolonged NK cell anti-tumour metabolic responses." (PMID 31595191, 2019). "A variety of cell culture studies have shown that ZnO NP can induce cytokines such as IFN-γ, TNF-α, IL-2, and IL-12 which are known to regulate the tumor microenvironment." (PMID 31771091, 2019). "Overall, our study revealed the therapeutic potential of tumor-targeting sumIL-2, a next-generation IL-2, for not only increasing half-life and reducing toxicity but also enhancing treatment effect by efficiently targeting CD8+ T cells inside tumor tissues." (PMID 31462678, 2019). "IL-2 secretion promotes T and B lymphocyte activity, enhances anti-tumor immunity, stimulates microglia, and regulates Tregs48–50." (PMID 31462642, 2019). "Combination of melatonin with interleukin-2 (IL-2) promoted tumor regression and improved 3-year survival in NSCLC patients." (PMID 31319607, 2019). "Logically, the incubation of PD-L1-expressing tumor cells with T cells was accompanied by inhibition of T cell activity, e.g. inhibition of IL-2 and IFN-γ secretion by T cells." (PMID 30699956, 2019). "The whole set of in vivo experiments showed that the introduction of K35E is compatible with immunostimulatory and anti-tumor activity of IL-2-derived molecules." (PMID 30692603, 2019). "Despite being less established, B cells can also activate an antigen presentation phenotype and play a role in driving anti-tumor responses upon engineering with chimeric IL-2 and TGF-β or IL-4 and GM-CSF." (PMID 31921109, 2019). "We found the combination of the two hemibodies to stimulate donor T cells to secrete interferon-γ (IFN-γ), interleukin-2 (IL-2), and to lyse tumor cells at half-maximal effective concentrations (EC50) of 290, 340, and 260 pM, respectively." (PMID 31772172, 2019). "In this study, we construct a recombinant IL-2 immunocytokine comprising a tumor-targeting antibody (Ab) and a super mutant IL-2 (sumIL-2) with decreased CD25 binding and increased CD122 binding." (PMID 31462678, 2019). "Compared with native IL-2, IL-2 superkine induce activation of T and NK cells resulting in improved anti-tumor responses in vivo with limited expansion of Treg." (PMID 31340613, 2019). "CD4+ T cells were selected for evaluation given their important role in producing IL-2 to support the optimization of tumor lysing CD8+ T cells." (PMID 31602007, 2019). "On the one hand membrane Hsp70 serves as a tumor-specific target for TKD/IL-2-activated NK cells, on the other hand, high cytosolic Hsp70 levels can interfere with apoptotic pathways that mediate radio-chemotherapy resistance." (PMID 30967859, 2019). "Further, the toxicity of IL-15 is less than that of IL-2, but the concentrations of IL-15 required to drive efficient anti-tumor function remain toxic." (PMID 31456796, 2019). "We also observed that mice receiving GQD and anti-mouse PD-1 combination therapy had lower levels of PD-1 and higher levels of IL-2 in tumour tissues." (PMID 31138779, 2019). "Then, we assessed the secretion of cytokines important for anti-tumor T cells responses, namely TNFα, IFNγ and IL-2." (PMID 31500665, 2019). "The most prominent anti-tumor cytolytic activity was achieved when PBL were stimulated with TKD/IL-2 concomitant with anti-PD-1 antibody (p < 0.001)." (PMID 30967859, 2019). "SKILs were tested for their capacity to produce T helper 1 (Th1) cell cytokines (IFN-γ and IL-2) or T helper 2 (Th2) cell cytokines (IL-5 and IL-10) upon co-culture with the tumor antigen peptides." (PMID 31727154, 2019). "ACT involves the isolation of TILs from a patient, cultured in the presence of IL-2 and evaluation of specific tumor recognition." (PMID 30841635, 2019).